VDR (vitamin D receptor)
Diseases named in the same sentence as VDR in open-access papers (continued):
Sharing a sentence is not in itself a finding about the gene and the disease.
colon carcinoma (113 papers, 2005 to 2025). "An association between VDR polymorphisms and the risks and outcomes of several malignancies such as colon cancer has been reported." (PMID 38329439, 2024). "On the other hand, the low expression of VDR in host with colon cancers have been linked to colon cancer disease development and progression and a slight improvement in relapse-free survival at 5 years after vitamin D supplementation." (PMID 38318147, 2024). "Studies have shown that VDR inhibits tumor progression by suppressing cell stemness in pancreatic cancer and colitis-associated tumorigenesis in colon cancer." (PMID 38639057, 2024). "A high VDR expression in contrast has been linked to lower mortality in primary breast, prostate, lung and colon cancers." (PMID 36362766, 2022). "In parallel to these findings, vitamin D receptor (VDR) has been proposed to play a role in colon cancer susceptibility and patient outcome." (PMID 35662320, 2022). "The transcription of the CST5 gene, encoding cystatin D, is strongly induced by 1,25(OH)2D3 in colon carcinoma cells via direct binding of VDR to its promoter region." (PMID 32854355, 2020). "The concentration of the microflora bacteria, leptin/LPR, and vitamin D/VDR has been associated with colon cancer as environmental factors." (PMID 31231490, 2019). "And VDR high expression was associated with better prognostic outcomes in colon cancer patients derived from GSE24551 and GSE39582 expression datasets." (PMID 31596728, 2019). "The results of our study are relevant for the clinic, as VDR expression is downregulated in approximately two-thirds of advanced colon tumors associated to the upregulation of SNAI1 and SNAI2 genes that code for SNAIL1/SNAIL2 transcriptional repressors." (PMID 21858154, 2011). "Studies have attempted to assess the effects of various single nucleotide polymorphisms (SNPs) of the vitamin D receptor (VDR) gene on the development of colon cancer." (PMID 22022386, 2011). "Subgroup analysis by cancer site showed that hypermethylation of VDR at significant CpG sites was inversely associated with both colon cancer risk (aOR, 0.32; 95% CI, 0.16–0.64; P = 0.001) and rectal cancer risk (aOR, 0.26; 95% CI, 0.12–0.57; P = 0.001) (Pheterogeneity = 0.65)." (PMID 37644572, 2023). "Vitamin D/vitamin D receptor (VDR) inadequacy is a major risk factor for colon cancer." (PMID 35982910, 2022). "As a result, VDR deficiency may cause lower levels of tocopherols, which may be indicative of an increased risk for colon cancer." (PMID 32355205, 2020). "VDR deficiency enhances Wnt/β-catenin signaling and tumor burden in colon cancer." (PMID 33145139, 2020). "Lower levels of tocopherols in HFD fed VDR deficient animals might be indicative of increased risk for colon cancer." (PMID 32355205, 2020). "Fifteen genes (DUSP2, INFGR1, IL6, IRF2, JAK2, MAP3K10, MMP1, NFkB1A, NOS2A, PIK3CA, SEPX1, SMAD3, TLR2, TYK2, and VDR) were associated with colon cancer mortality (PARTP <0.05); JAK2 (PARTP = 0.0086), PIK3CA (PARTP = 0.0098), and SMAD3 (PARTP = 0.0059) had the strongest associations." (PMID 25541970, 2014). "Fifteen genes (DUSP2, INFGR1, IL6, IRF2, JAK2, MAP3K10, MMP1, NFkB1A, NOS2A, PIK3CA, SEPX1, SMAD3, TLR2, TYK2, and VDR) were significantly associated with colon cancer mortality at the <0.05 level; an additional 15 genes had gene PARTP values between 0.05 and 0.10." (PMID 25541970, 2014). "Loss of VDR expression during colon cancer progression is related to Snail up-regulation, suggesting that high levels of Snail may be responsible for the failure of therapy with vitamin D analogues in patients." (PMID 23341935, 2013). "Therefore, VDR is an important contributor to host protection from bacterial infection and associated with colon tumor progress." (PMID 21414188, 2011). "In this study we examined whether VDR deficiency alters β-catenin nuclear content and Wnt/β-catenin pathway in the most commonly used animal model for colon cancer, the Apcmin/+ mice." (PMID 21858154, 2011).
colon carcinoma (continued). "Since SNAIL is upregulated during human colon cancer progression, which is associated with reduced VDR expression, the analysis of SNAIL expression may help to select patients suitable for therapy with vitamin D analogues." (PMID 15770204, 2005). "For example, in colon cancer, it has been seen that vitamin D has demonstrated therapeutic potential but may be limited due to VDR mutations, and a combinatorial approach of a rexinoid and a VDR ligand could help mitigate any effects of VDR mutations." (PMID 39594626, 2024). "Other studies in vitro have also indicated that VDR suppresses cell proliferation in colon cancer and VDR participates the inhibition of epithelial-mesenchymal transition in human laryngeal squamous cell carcinoma." (PMID 38639057, 2024). "For instance, in colon cancer, VDR mRNA is decreased, while the opposite is true for basal cell carcinoma, squamous cell carcinoma, and breast, cervical, and ovarian cancers, suggesting a tissue-specific effect of VDR signaling." (PMID 38318147, 2024). "VDR signaling also interacts with critical pathways involved in colon cancer, such as Wnt/β-catenin, PI3K/Akt, and MAPK signaling." (PMID 38372868, 2024). "VDR was first identified as a biomarker for vitamin D-mediated suppression of cell proliferation in human colon cancer." (PMID 38372868, 2024). "The activation of VDR by its ligands, such as 1,25-dihydroxyvitamin D3 (calcitriol), impacts gene expression and many cellular processes in colon cancer cells." (PMID 38372868, 2024). "The VDR plays a crucial role in the butyrate-mediated inhibition of NF-κB activation in human colon cancer cells." (PMID 39224217, 2024). "To validate the anti-PD-L1 effects of MeTC7 in vivo, we utilized a syngeneic colon cancer model in which radiation therapy (RT) induces overexpression of both VDR and PD-L1 on tumor cells." (PMID 37444542, 2023). "A conditioned medium from probiotic lactic acid bacteria showed increased expression of VDR and of its target CAMP gene encoding cathelicidin in cultured colon carcinoma cells and organoids." (PMID 35406059, 2022). "As expected, DSS increased colon tumor multiplicity in ApcPirc/+VDR+/+ rats (females 9.5±4.0, males 49.7±13.8) versus matched untreated controls (females 1.5±1.4, males 4.8±2.1, P<0.0001)." (PMID 35662320, 2022). "We review the impacts of VDR on barriers in various diseases, e.g., colon cancer, infection, inflammatory bowel disease, and chronic inflammatory lung diseases." (PMID 35406694, 2022). "This is in line with previous studies showing that overexpression of the VDR appears in chemoresistant colon cancer cells." (PMID 36291915, 2022). "VDR plays multiple functional roles of in the development of colon cancer; thus, it is important to dissect the mechanisms by which VDR contributes to barrier function in protecting the host from tumorigenesis." (PMID 35406694, 2022). "Calcitriol affects different colon cancer cell lines containing an adequate level of vitamin D receptors (VDR)." (PMID 35433131, 2022). "In patients with pancreatic ductal adenocarcinoma (PDAC) and colon cancer, vitamin A deficiency led to PSC activation in PDAC patients, while a previous study showed that the vitamin D receptor (VDR) was a suppressor of PSC activation." (PMID 36046791, 2022). "Emerging evidence demonstrates that vitamin D/VDR deficiency is a critical factor in the pathology of many diseases, such as IBD and colon cancer, among others." (PMID 35406694, 2022). "Experiments with colon cancer cells confirmed the results and identified the pro-apoptosis targets of VDR." (PMID 36364774, 2022). "The methylation of CpG island in the VDR promoter region has been related to decreased VDR expression in breast and colon cancer cells." (PMID 34208589, 2021). "VDR is expressed in normal colon epithelial cells and by some colon cancer cells at variable levels." (PMID 34359694, 2021).
colon carcinoma (continued). "Concordantly, the analysis of a large cohort of colon cancer patients indicated that the expression of VDR in CAFs and carcinoma cells has an additive protective effect, extending the overall survival of patients." (PMID 32854355, 2020). "The effects were shown both in vivoand vitro with the help of Apcmin/+Vdr-/- mice and cultured human colon cancer cells in which shRNA was used to knock down the expression of VDR." (PMID 33145139, 2020). "In SW480 colon cancer cells, 1,25(OH)2D3 promoted VDR/β-catenin interaction and prevented the β-catenin translocation into the nucleus." (PMID 33291213, 2020). "All those results suggest that similar with CDX2, VDR is also an important prognostic biomarker for colon cancer patients." (PMID 31596728, 2019). "In the preclinical studies, the contradictory outcomes have observed the VDR gene expression in colon cancer models." (PMID 31231490, 2019). "CDX2 and VDR expression level in the three sub-clusters of colon cancer patients were also significantly different." (PMID 31596728, 2019). "In fact, the expression and the activation of VDR promotes the differentiation of colon carcinoma cells." (PMID 29743643, 2018). "The 1,25D ligand-activated VDR in colon carcinoma cells competes with a β-catenin binding member (Tcf4) for β-catenin binding." (PMID 30314996, 2018). "For instance, the expression of the nuclear receptor for Vitamin D (VDR) genes were selectively upregulated by MVs from V. cholerae in colon carcinoma cells." (PMID 29743643, 2018). "The expression of K-Ras mutants in human colon cancer cells and H-Ras mutants in mouse colon and rat intestinal epithelial cells inhibit calcitriol-dependent VDR activation by suppressing VDR transcription." (PMID 29657326, 2018). "In colon cancer lines, calcitriol induces the VDR to directly bind to β-catenin and increases E-cadherin expression to sequester β-catenin at adherens junctions, which leads to a reduced Wnt pathway activation." (PMID 29581858, 2018). "Vitamin D and VDR affect Wnt signaling through a direct interaction with β-catenin, resulting in the attenuation of growth in colon cancer cells." (PMID 29176823, 2017). "Other studies showed absence of correlation or a significant direct correlation between ZEB1 and VDR RNA expression in colon cancer." (PMID 26880977, 2016). "In another study for colon cancer, the author reported that expression of VDR was negatively correlated with those of snail and ZEB1 in the cancer tissue." (PMID 27548154, 2016). "Remarkably, SNAIL1 and/or SNAIL2 RNA upregulation was detected in 76% of colon tumors and significantly correlated with diminished VDR RNA expression." (PMID 26880977, 2016). "Ligand-dependent VDR signaling has been shown to antagonize the β-catenin signaling pathway through several mechanisms in human and murine colon cancer cells." (PMID 26008979, 2015). "Similar to colon cancer, 1,25D3 dose-dependently increased expression of the extracellular canonical Wnt inhibitor, DKK-1, in R7 cells while loss of VDR in MMTV-Ron mice reduced tumoral DKK-1 mRNA." (PMID 26008979, 2015). "Cystatin D presumably plays an important role as a mediator of tumor suppression in colon cancer cells and is directly induced by the VDR." (PMID 26158294, 2015). "It is also well established that the VDR is expressed by normal colon epithelial cells, but its expression is decreased during the progression of colon cancer." (PMID 26260259, 2015). "Due to the antagonistic role of VDR on β-catenin signaling in human colon cancers, in this study the role of VDR in Ron-induced mammary tumorigenesis was investigated." (PMID 26008979, 2015). "Recently, CST5 was shown to be induced by vitamin D3 via direct binding of the vitamin D receptor (VDR) to its promoter in human colon cancer cell lines." (PMID 26158294, 2015).
colon carcinoma (continued). "The anti-cancer properties of vitamin D can influence the process of proliferation, differentiation and apoptosis of human colon cancer cells mainly through vitamin D receptor (VDR)." (PMID 26205949, 2015). "This confirms the anti-proliferative function of vitamin D and VDR which has been described for the colon and colon carcinoma cells." (PMID 24641763, 2014). "For instance, it has been reported that downregulation of VDR correlates with poor prognosis in colon cancer, suggesting that some of the discrepancy observed in epidemiological studies can be explained through gene polymorphisms." (PMID 25255691, 2014). "At the same time, high VDR expression correlates with an advantageous prognosis in colorectal patients, suggesting an important role for VDR in the pathogenesis of colon cancer." (PMID 24919507, 2014). "Another study indicated that vitamin D analogs appear to be mediated by ligand-activated VDR competing with transcription T cell factor-4 for β-catenin biding, enhancing the differentiation of colon carcinoma cells by inhibiting β-catenin signaling." (PMID 23690997, 2013). "Our group found that the transcription factors Snail1 and Snail2 repress VDR expression and block the antitumoral actions of 1,25(OH)2D3 in cultured colon cancer cells and in xenografted mice, including the inhibition of Wnt/β-catenin signaling." (PMID 24202444, 2013). "The G0S2 gene is a simple example with only one VDR binding site within its chromosomal domain, which is used in all published VDR ChIP-seq data sets besides that from colon cancer cells." (PMID 24202443, 2013). "In this review we focus on the crosstalk between VDR and Wnt/β-catenin signaling in cancer, with special emphasis on colon cancer, and the functional outcome of this interaction." (PMID 24202444, 2013). "Accordingly, high SNAIL1/2 expression in cultured colon cancer cells increases β-catenin transcriptional activity by repressing VDR expression and its antagonistic activity on Wnt/β-catenin signaling." (PMID 21858154, 2011). "Consistently, knocking-down VDR by shRNA in human colon cancer cells enhances the nuclear content of β-catenin, its transcriptional activity, and the expression of Wnt/β-catenin target genes." (PMID 21858154, 2011). "Here we describe that vitamin D receptor (VDR) is a crucial modulator of nuclear β-catenin levels in colon cancer in vivo." (PMID 21858154, 2011). "mRNA levels of PXR, CYP3A4 and vitamin D receptor (VDR) were evaluated by quantitative real-time PCR on 6 colon cancer cell lines (Caco-2, HT29, HCT116, SW48, LS180, and LoVo)." (PMID 21342487, 2011). "To demonstrate a causal link between VDR loss and the increase in nuclear β-catenin, we studied SW480-ADH human colon cancer cells in which VDR was knocked-down by means of shRNA." (PMID 21858154, 2011). "In conclusion, VDR controls the level of nuclear β-catenin in colon cancer cells and can therefore attenuate the impact of oncogenic mutations that activate the Wnt/β-catenin pathway." (PMID 21858154, 2011). "Transient expression of exogenous wild type VDR in VDR-negative human SW620 metastatic colon cancer cells reduced their high nuclear β-catenin levels." (PMID 21858154, 2011). "Our initial description of the direct interaction of β-catenin with VDR in human colon cancer cells has been confirmed in other cell systems." (PMID 21858154, 2011). "A few studies have proposed VDR expression as a marker of good prognostic in colon cancer and showed its correlation with high tumor differentiation and absence of node involvement." (PMID 21858154, 2011). "In line with this, VDR knock-down in cultured human colon cancer cells enhanced β-catenin nuclear content and target gene expression." (PMID 21858154, 2011). "Our results reveal a novel in vivo function of VDR as crucial modulator of Wnt/β-catenin signal strength in colon cancer." (PMID 21858154, 2011).
colon carcinoma (continued). "Our results establish a direct link between VDR function and nuclear β-catenin levels that is crucial to control the activity of Wnt/β-catenin signaling in colon cancer in vivo." (PMID 21858154, 2011). "The MED24 (mediator complex subunit 24) gene acts indirectly on VDR, a 4T1-upregulated gene in our data, which functions to inhibit p38 activity – a known mediator of tumor cell death in colon cancer." (PMID 20700505, 2010). "Altered VDR protein expression has been reported in a number of tumor types including breast, malignant gliomas, prostate, and colon cancer." (PMID 19753122, 2009). "These cells also express VDR, but at lower (i.e. normal) levels with respect to several other colon cancer cell lines." (PMID 19924301, 2009). "Although all cell types investigated had been shown to express ER-α and -β as well as the VDR, IL-6 expression in human colon carcinoma cells was only modestly, if at all, influenced by the steroid hormones 17β-E2 and 1,25-(OH)2D3." (PMID 18205904, 2008). "In human skin tumours with detectable nuclear β-catenin, the level of VDR correlates with differences in tumour phenotype, a similar situation to human colon cancer." (PMID 18213391, 2008). "Our group observed that in a panel of human colon cancer cell lines, high SNAIL expression associates with undifferentiation and low VDR and E-cadherin expression, and vice versa." (PMID 15770204, 2005). "Recent data have shown that SNAIL represses VDR gene expression in cultured human colon cancer cells, leading to hormone unresponsiveness in vitro and in vivo." (PMID 15770204, 2005). "Our data indicate that colon cancer patients with SNAIL upregulation express low VDR and are thus likely to be poor responders to vitamin D analogues." (PMID 15770204, 2005). "VDR is also lost at late stages of colon cancer progression, impairing the induction of E-cadherin by 1,25(OH)2D3." (PMID 15770204, 2005). "Similarly, in HCT-116 colon cancer cells, VDR expression was significantly increased, whereas TNFα expression showed no statistically significant change." (PMID 41444742, 2025). "However, colon cancer cells, including HCT-116, often exhibit reduced VDR levels, which are associated with worse prognosis." (PMID 41444742, 2025). "Immunohistochemical analysis of human colon tumor tissue microarrays (TMAs) from the Biobank of Hospital Clínico San Carlos (HCSC, Madrid) revealed a significant (p=0.017) positive association between the levels of VDR and SIRT1 proteins." (PMID 37530744, 2023). "The active vitamin D metabolite (1α,25-dihydroxyvitamin D3 or calcitriol) inhibits proliferation and promotes the epithelial differentiation of human colon carcinoma cell lines that express the vitamin D receptor (VDR) via the regulation of a large number of genes." (PMID 35276999, 2022). "Furthermore, the downregulation of the VDR has been correlated with worse clinical outcomes in, e.g., breast, prostate and colon cancer patients." (PMID 36362766, 2022). "VDR expression and activity degradation may be a common molecular change observed in a variety of tumor types, including breast, prostate and colon cancer." (PMID 35884356, 2022). "However, in advanced cancers, VDR expression decreases or even disappears entirely, indicating that colon cancer cells can only express VDR as long as they maintain a certain level of differentiation." (PMID 34359694, 2021). "Interestingly, a recent study showed that the SOX2 gene promoter was directly repressed from vitamin D receptor (VDR) occupancy on VDR elements in colon cancer cells." (PMID 34503224, 2021). "It has been observed that the expression of H-Ras mutants in rat intestinal epithelial cells and mouse colon as well as the expression of K-Ras mutants in human colon cancer cells suppress calcitriol-mediated activation of VDR activation by inhibiting VDR transcription." (PMID 34208589, 2021).